PML (PML nuclear body scaffold)
Diseases named in the same sentence as PML in open-access papers (continued):
Sharing a sentence is not in itself a finding about the gene and the disease.
acute promyelocytic leukemia (continued). "ANXA8 upregulation was found upregulated for the first time in acute promyelocytic leukemia (APL) with repressed wild-type RARA transcriptional function due to dominant negative RARA fusion proteins as PML-RARA." (PMID 30678048, 2019). "All-trans retinoic acid (ATRA) is used in the treatment of acute promyelocytic leukemia (APL), which is characterized by a chromosomal translocation involving the retinoid-receptor, RARα, resulting in the production of the PML-RARα oncogene." (PMID 30532072, 2019). "Targeting PML in acute promyelocytic leukemia (APL) with all-trans retinoic acid and/or arsenic trioxide results in PML degradation and triggers cycling of the quiescent APL LSCs." (PMID 31127148, 2019). "In cases of acute promyelocytic leukemia (APL), the PML-RARα fusion gene has been proven to be the driver gene, and thereby, chemical agents targeting this gene show a therapeutic effect." (PMID 31598153, 2019). "In acute promyelocytic leukemia (APL), a chromosomal translocation involving chromosomes 15 and 17 leads to the creation of the PML-retinoic acid receptor-α (PML-RARα) fusion oncoprotein." (PMID 30991648, 2019). "The vast majority of acute promyelocytic leukemia (APL) is characterized with a specific chromosomal translocation t (q22, q21), which fuses PML-RARα leading to a good response to all-trans retinoic acid (ATRA) and arsenic trioxide (ATO)." (PMID 31083206, 2019). "Acute promyelocytic leukemia (APL) is a distinct subtype of acute myeloid leukemia that is mostly driven by the chimeric oncoprotein PML-RARA." (PMID 30992691, 2019). "Acute promyelocytic leukemia (APL) is a subgroup of acute myeloid leukemia, most commonly characterized by chromosomal translocation that generates PML-RARα fusion protein." (PMID 31396278, 2019). "Promyelocytic leukemia-retinoic acid receptor α (PML-RARa) sets the cellular landscape of acute promyelocytic leukemia (APL) by repressing the transcription of RARa target genes and disrupting PML-NBs." (PMID 31635329, 2019). "Acute promyelocytic leukemia (APL) is a special kind of acute myeloid leukemia (AML) characterized by the presence of PML/RARα fusion gene located on chromosome 15 and chromosome 17, respectively." (PMID 30200136, 2018). "In addition to the well‐known effects on blocking myeloid differentiation at the promyelocytic stage, promyelocytic leukaemia‐retinoic acid receptor α (PML‐RARα) has also been reported to interfere with multiple differentiation processes, including erythroid differentiation." (PMID 30320491, 2018). "Acute promyelocytic leukemia (APL) is characterized by expression of the promyelocytic leukemiahetinoic acid receptor alpha gene (PML/RARa;PR)." (PMID 30607328, 2018). "The role of S100A10 in cancer was first identified in acute promyelocytic leukemia (APL), a subtype characterized by the expression of a fusion protein formed by the fusion of retinoic acid receptor alpha with promyelocytic leukemia (PML-RARα) genes." (PMID 30572596, 2018). "Arsenic trioxide (ATO, As2O3) is an inorganic compound which has been proven successful in treating PML-RARα positive acute promyelocytic leukemia (APL) through SUMOylation and ubiquitination of the PML-RARα mutant." (PMID 30250637, 2018). "For this, we used the NB4 human APL cell line, which has the 15;17 chromosomal translocation leading to the production of the PML-RARα fusion protein, that is characteristic for the majority of acute promyelocytic leukemia cases." (PMID 28343272, 2017). "Treatment of acute promyelocytic leukemia (APL) with AS2O3 has unique favorable cure rates, and the major mechanism of action is through the degradation of PML-RARα, the driver of APL." (PMID 26934650, 2016). "Proteins involved in DNA double-strand break (DSB) repair localize within the promyelocytic leukemia nuclear bodies (PML-NBs), whose disruption is at the root of the acute promyelocytic leukemia (APL) pathogenesis." (PMID 27468685, 2016).
acute promyelocytic leukemia (continued). "All-trans retinoic acid (ATRA) treatment yields cure rates > 80% through proteasomal degradation of the PML-RARα fusion protein that typically promotes acute promyelocytic leukemia (APL)." (PMID 26673819, 2016). "Selective targeting of the PML/RARα oncoprotein demonstrates a successful molecular targeted therapy in acute promyelocytic leukemia (APL) with a typical t(15:17) chromosomal translocation." (PMID 27732960, 2016). "Acute promyelocytic leukemia (APL) is characterized by a balanced reciprocal translocation between chromosomes 15 and 17, which leads to the expression of the fusion protein PML-RARα." (PMID 26545364, 2015). "Two successful examples of targeted therapies in pediatric leukemia include tyrosine kinase inhibitors in BCR-ABL-positive ALL and all-trans retinoic acid (ATRA) in acute promyelocytic leukemia (APML) with the PML–RARα fusion." (PMID 25295230, 2014). "Acute promyelocytic leukemia (APL), a subtype of acute myeloid leukemia characterized by the formation of a PML-RARα fusion protein, leads to the accumulation of abnormal promyelocytes." (PMID 25369030, 2014). "We have studied the role of HIF-1α in acute promyelocytic leukemia (APL), a sub-type of acute myeloid leukemia characterized by expression of the fusion protein PML-RARα." (PMID 24711541, 2014). "ATO directly binds to cysteine residues in the PML-RARα oncoprotein that is expressed in patients suffering from acute promyelocytic leukemia (APL)." (PMID 24970215, 2014). "PML protein has been extensively studied because of its involvement in the etiology of Acute Promyelocytic Leukemia (APL)." (PMID 23555679, 2013). "The tumor suppressor promyelocytic leukemia (PML) protein is fused to the retinoic acid receptor alpha in patients suffering from acute promyelocytic leukemia (APL)." (PMID 23734343, 2013). "In Acute Promyelocytic Leukemia (APL), fusions between Promyelocytic Leukemia (PML) and Retinoic Acid Receptor (RAR) recruit HDACs resulting in the repression of differentiation-related genes." (PMID 22550500, 2012). "PML is a tumor suppressor protein as first realized in acute promyelocytic leukemia (APL), where a chromosomal translocation creates a fusion protein with the retinoic acid receptor α, resulting in loss of PML function." (PMID 21998700, 2011). "In acute promyelocytic leukemia (APL), retinoid receptor function is disrupted, demonstrated by the inhibition of RARA caused by a chromosomal translocation that creates the PML/RARA fusion protein, which blocks the differentiation of myeloid cells and drives cancer cell proliferation." (PMID 41155227, 2025). "The disarray of PML NBs in acute promyelocytic leukemia (APL) led to their discovery." (PMID 41268324, 2025). "We noted that human acute promyelocytic leukemia (APL) samples, a subtype of AML initiated by the PML::RARA fusion gene, had markedly higher expression of GAB2 than most other AMLs." (PMID 40773291, 2025). "In APL with fusion gene PML::RARA, miR-15b is described to have an essential function in the proliferation and differentiation of acute promyelocytic leukemia." (PMID 40282406, 2025). "Acute promyelocytic leukemia (APL) is a subtype of acute myeloid leukemia defined by the presence of a genetic abnormality, namely the PML::RARA gene fusion, as the result of a reciprocal balanced translocation between chromosome 17 and chromosome 15." (PMID 40095699, 2025). "Acute promyelocytic leukemia (APL) is a subtype of AML, classified by a translocation between chromosomes 15 and 17 involving the PML and RARA genes and morphologically characterized by the accumulation of abnormal promyelocytes in the blood and bone marrow." (PMID 40414700, 2025). "YOD1 regulates the stability of PML/RARα, CDK1, and ITCH, promoting malignant phenotypes in acute promyelocytic leukemia, triple-negative breast cancer, and hepatocellular carcinoma, respectively." (PMID 40274778, 2025).
acute promyelocytic leukemia (continued). "In acute promyelocytic leukemia (APL), HIF-1α collaborates with the PML-RARα fusion protein to maintain leukemia stem cell self-renewal and promote tumor neovascularization and migration." (PMID 40791591, 2025). "APL with PML‐RARA fusion, a distinct subtype of acute myeloid leukemia (AML), is characterized by the presence of the promyelocytic leukemia‐retinoic acid receptor alpha (PML‐RARA) fusion gene." (PMID 40251942, 2025). "Acute promyelocytic leukemia (APL), characterized by the PML-RARA fusion oncogene, represents 5–10% of acute myeloid leukemia (AML) cases with distinct clinical urgency due to rapid progression and life-threatening coagulopathy." (PMID 41204132, 2025). "An analogous successful approach can be seen in the treatment of acute promyelocytic leukemia (APL), where the combination of all-trans retinoic acid (ATRA) and arsenic trioxide (ATO) targets different moieties of the PML-RARα fusion oncoprotein." (PMID 39682203, 2024). "In acute promyelocytic leukemia (APL), chromosomal translocation leads to the formation of a heterodimer (PML-RARα) between PML and retinoic acid receptor α (RARα)." (PMID 38383403, 2024). "Here, we identify USP22 as regulator of PML and the oncogenic acute promyelocytic leukemia (APL) fusion PML-RARα protein stability and identify a destabilizing role of PML residue K394." (PMID 38467608, 2024). "Autophagy of acute promyelocytic leukemia cells is induced by exposure to retinoic acid or arsenic trioxide (ATO), and it is essential for the degradation of PML-RARα fusion protein by retinoic acid or ATO." (PMID 38069042, 2023). "PML, identified in the fused protein of retinoic acid receptor (RAR)/PML in acute promyelocytic leukemia, is one of the early cancer targets for targeted drug therapy." (PMID 38069029, 2023). "For example, acute promyelocytic leukemia (APL) exhibits a characteristic immunophenotype (CD34−, HLA-DR−, CD117+, CD15−) that can prompt PML::RARA gene fusion evaluation and consequent management until the molecular result is available." (PMID 37366878, 2023). "Differentiation therapy, i.e., all-trans retinoic acid (ATRA) and arsenic trioxide, has been shown to be an effective treatment for acute promyelocytic leukemia (APL), a distinct AML subtype characterized by the expression of the PML/RARA fusion protein." (PMID 37828578, 2023). "The proband was a 42-year-old female patient with acute promyelocytic leukemia (APL) and PML-RARα fusion gene." (PMID 36998465, 2023). "In an in vivo experimental model of acute promyelocytic leukemia (APL), specifically the PML/RARα model, green tea was found to increase the levels of reactive oxygen species (ROS) within bone marrow Gr1+ cells, simultaneously decreasing the number of CD34+ and CD117+ cells." (PMID 37513933, 2023). "In cancers, SUMOylation of promyelocytic leukemia/retinoic acid receptor alpha (PML/RARA) is important for cellular transformation and essential for the pathogenesis of acute promyelocytic leukemia." (PMID 37201027, 2023). "In an acute promyelocytic leukemia (APL) model (PML/RARα), green tea treatment reduced blast percentages (CD34 and/or CD117) in the bone marrow and spleen possibly through the induction of apoptosis and reduction in the CXCR4/HIF-1α signaling pathway in response to a decrease in ROS levels." (PMID 37513933, 2023). "This experiment provides a therapeutic model approach for the acute promyelocytic leukemia (APL) disease, in which a translocation results in PML gene knockout." (PMID 35232993, 2022). "Here, we assess the cell mechanics of acute promyelocytic leukemia (APL), an acute myeloid leukemia (AML) subtype characterized by a fusion gene between PML (promyelocytic leukemia protein) and RARA (retinoic acid receptor alpha)." (PMID 35141508, 2022). "PML-RARA is the fusion gene responsible for acute promyelocytic leukemia (APL)." (PMID 35159934, 2022).
acute promyelocytic leukemia (continued). "PML/RARA (promyelocytic leukemia/retinoic acid receptor A) fusion protein can block the differentiation and maturation of granulocytes, which is the main cause of APL (acute promyelocytic leukemia)." (PMID 35433636, 2022). "Acute promyelocytic leukemia (APL) is characterized by the balanced translocation of chromosomes 15 and 17, resulting in the formation of PML-RARA fusion gene." (PMID 36212492, 2022). "Valleron et al14 found that the expressions of snoRNAs in SNORD112-114 cluster were significantly increased in patients with acute promyelocytic leukemia (APL), which was correlated with PML-RARα." (PMID 36518603, 2022). "We investigated the IFNα mechanism of action focusing on PML, an interferon target and key senescence gene whose targeting by arsenic trioxide (ATO) drives eradication of acute promyelocytic leukemia." (PMID 33075130, 2021). "For example, arsenic trioxide (As2O3, Trisenox®) has been used as standard monotherapy in acute promyelocytic leukemia (APL), which is a rare case of acute myeloid leukemia (AML), targeting the PML/RARA oncogene." (PMID 33558527, 2021). "A tumor-suppressive role for RNF4 was discovered in acute promyelocytic leukemia (APL), in which the oncogenic driver is a fusion protein that combines the promyelocytic leukemia protein (PML) with RARα (PML-RARα)." (PMID 34572023, 2021). "Regarding Acute Promyelocytic Leukemia (APL), an aggressive subtype of AML, SETDB1 is a stable member and responsible for the integrity of PML-NBs which are found interspersed in chromatin, regulating transcription, apoptosis and DNA damage responses." (PMID 34440561, 2021). "The last two issues allow to overcome the RT-qPCR limitations in monitoring several fusion transcripts, such as both canonical and atypical BCR–ABL1 breakpoints in CML patients and PML/RARA in acute promyelocytic leukemia (APL), guiding the therapeutic strategy." (PMID 34771634, 2021). "PML degradation releases pro-apoptotic factors and induces apoptosis in response to arsenic treatment, a standard therapy for the treatment of acute promyelocytic leukemia (APL)." (PMID 34065507, 2021). "The PML gene fuses with the retinoic acid receptor‐α (RAR-α) gene, resulting in the PML protein in acute promyelocytic leukemia and disrupting the PML nuclear bodies." (PMID 32737302, 2020). "For example, this has been shown in acute promyelocytic leukemia (APL), where ATO is already used in the clinic, and binds to PML and the PML-RARα fusion protein that is found in almost all APL-cells." (PMID 30871073, 2019). "Here the authors determine the crystal structure of a PML B1-box multimer and characterise the oligomerisation behaviour of the PML RBCC construct and show that disrupting B1-B1 interactions precludes promyelocytic leukemia leukemogenesis in transgenic mice." (PMID 31439836, 2019). "In promyelocytic leukemia/retinoic acid receptor α (PML-RARα)-positive leukemic cells, JMJD3 was found activated by the PML-RARα fusion protein and enhance expression of homeobox (HOX) gene." (PMID 31701394, 2019). "In particular, the PML/RARα translocation, which characterizes a subtype of AML referred to as acute promyelocytic leukemia (APL), produces oncogenic f-circRNAs that have been shown to favor leukemia progression in transgenic mouse models." (PMID 31024852, 2019). "The advantage of identifying by molecular methods MRD levels predictive of clinical relapse has been proven for acute promyelocytic leukemia (APL), where a positive PML-RARA test after the end of consolidation therapy is invariably associated to overt relapse." (PMID 31396481, 2019). "Nowadays, it is clinically used to treat acute promyelocytic leukemia (APL) by targeting PML/RARA." (PMID 29535630, 2018). "Acute promyelocytic leukemia (APL) is a kind of acute myeloid leukemia, which was characterized by the presence of PML/RARα fusion gene." (PMID 30200136, 2018).
acute promyelocytic leukemia (continued). "PML is known for its role in the pathogenesis of acute promyelocytic leukemia (APL)." (PMID 30379886, 2018). "They demonstrated that many recurrent chromosomal translocations, of PML/RARα observed in Acute Promyelocytic Leukemia (APL), MLL/AF9 in Acute Myeloid Leukemia (AML), EWSR1/FLI1 in Ewing Sarcoma and EML4/ALK1 associated with lung cancer could form f-circRNAs." (PMID 30018188, 2018). "On the other hand, autophagy induced by ATRA and/or As2O3 contributes significantly to the degradation of oncoproteins such as PML/RARα and BCR-ABL and the regulation of therapy-induced differentiation in the case of acute promyelocytic leukemia." (PMID 28404874, 2017). "After these first indications, we described a pro-leukemogenic function of HIF-1α in a specific sub-type of AML, that is acute promyelocytic leukemia or AML-M3, due to a specific functional cooperation of HIF-1α with the oncogenic fusion protein PML-RARα." (PMID 27447550, 2016). "Only between 1 and 3 PML bodies are found in the acute promyelocytic leukemia-derived NB4 cell line, in a background of numerous micro-PML foci." (PMID 27389808, 2016). "Acute promyelocytic leukemia (APL), characterized by the t chromosomal translocation and leukemogenic PML-RARα fusion protein, is accumulated of abnormal promyelocytes in the bone marrow and causes severe bleeding tendency." (PMID 25122165, 2014). "Other studies were devoted to analyze the cooperation between PML-RARA and FLT3-ITD in promoting the development of acute promyelocytic leukemia (APL)." (PMID 23936658, 2013). "This process is a key mechanism of action of As2O3 resulting in the degradation of PML and PML-RARα in APL (see Targeting PML-RARα to Treat Acute Promyelocytic Leukemia)." (PMID 23730625, 2013). "Promyelocytic leukemia NBs provide an intrinsic host defense against VZV infection and the ORF61 SIM-dependent PML NB disruption is used by VZV to counteract the antiviral activity of these nuclear structures." (PMID 23734343, 2013). "Moreover, arsenic trioxide-induced autophagy through inhibiting the mTOR pathway contributes to degradation of the PML/RARA fusion protein in acute promyelocytic leukemia (APL)." (PMID 22829831, 2012). "The PML protein was originally discovered in patients suffering from acute promyelocytic leukemia (APL), where a reciprocal chromosomal translocation resulting in a fusion of the PML protein to the retinoic acid receptor α turned out to be responsible for this hematopoietic malignancy." (PMID 21994592, 2009). "Notably, the PML-RARA fusion protein promotes the expansion of leukemia cells by obstructing normal myeloid differentiation via the retinoic acid receptor (RAR) signaling pathway in acute promyelocytic leukemia (APL)." (PMID 40753178, 2025). "For example, in acute promyelocytic leukemia (APL), disrupting the PRC2/EZH2 complex can not only reverse histone modifications but also induce DNA demethylation of PML-RARα target genes, which, in turn, reactivates differentiation-related genes and promotes cell differentiation." (PMID 39655332, 2024). "Importantly, PCR assays have been developed for three AML phenotypes: (i) acute promyelocytic leukemia (APL) (fusion gene PML::RARA); (ii) patients with NPM1 and CBF–AML (RUNX1::RUNX1T1 and CBFB::MYH11); and (iii) AML with fusion genes BCR::ABL1, KMT2::MLLT3, and DEK::NUP214." (PMID 37345204, 2023). "PML, also known as TRIM19, which was originally found in Acute Promyelocytic Leukemia." (PMID 36776317, 2023). "ATRA targeting of the oncogenic PML–RARα fusion protein, together with the use of arsenic trioxide, has provided a cure for most patients with acute promyelocytic leukemia, but ATRA has failed to provide an effective treatment for other cancers." (PMID 37569466, 2023).